TNF (tumor necrosis factor)
Diseases named in the same sentence as TNF in open-access papers (continued):
Sharing a sentence is not in itself a finding about the gene and the disease.
hyperuricemia (continued). "Experimental studies have shown that hyperuricemia leads to elevated levels of agents of systemic inflammation such as interleukin 6 (IL-6), tumor necrosis factor a (TNF-a) and C-reactive protein (CRP)." (PMID 31815071, 2019). "In animal study, hyperuricemia rats showed increased kidney inflammation (TNF-α), fibrotic(TGF-β) and oxidative (HO-1) markers, along with pathologically confirmed kidney fibrosis." (PMID 29619870, 2018). "In this study, we demonstrated that infiltration of T cells and macrophages were markedly increased in hyperuricemia mice kidney, accompanied by an up-regulation of TNF-α, MCP-1 and RANTES expression." (PMID 22761883, 2012). "We further investigated the expression of TNF-α, an inflammatory cytokine probably produced by infiltrated cells in hyperuricemia mice kidneys." (PMID 22761883, 2012). "In comparison to the CON group, the mRNA levels of inflammatory and stress markers, including IL-1β, TNF-α, and IL-6, were approximately twofold higher (p < 0.001) in the hyperuricemia group, indicating a significant upregulation of these genes in response to hyperuricemia (HUA)." (PMID 41009565, 2025). "As expected, the concentrations of multiple inflammatory cytokines including tumor necrosis factor-alpha (TNF-α), interleukin-1 beta (IL-1β) and interleukin-6 (IL-6) were higher in the kidney of the hyperuricemia group than those in the CON group, indicating the presence of inflammation." (PMID 41009565, 2025). "In the preceding results, it was observed that EST could effectively reduce the expression levels of inflammatory cytokines PGE2, IL-1β, and TNF-α in PO-induced hyperuricemia mice." (PMID 38540830, 2024). "Besides, the urate‐associated inflammation reflected by IL‐6, TNF‐α and diamine oxidase (DAO) levels in serum of hyperuricemia rats were also alleviated." (PMID 36925686, 2023). "Moreover, it lessens renal concentrations of TNF-α, IL-1β, and IL-6 in mouse models of hyperuricemia, thereby mitigating renal impairment." (PMID 38094893, 2023). "Increased LPS and TNF levels in hyperuricemic mice have suggested the possibility that hyperuricemia, at least in mice, induces a state of low-grade systemic inflammation that could modify lipid metabolism in the liver." (PMID 35879786, 2022). "Hyperuricemia can promote the expression of inflammatory cytokines, such as IL-1β, TNF-α, and IL-6." (PMID 34444825, 2021). "Furthermore, bergenin decreased the serum levels of IL-6, IL-1β, and TNF-α in hyperuricemia mice, and promoted a polarization shift from the M1 to M2 phenotype in RAW264.7 cells." (PMID 32850823, 2020). "Importantly, no significant alterations in serum LPS, IL-1β, TNF-α, or intestinal permeability were observed before the onset of hyperuricemia (on the 3rd), confirming the association between hyperuricemia and systemic inflammation." (PMID 38088975, 2023). "Clinical data indicate that patients with hyperuricemia or uric acid nephropathy exhibit significantly higher levels of low-grade inflammatory markers, such as hs-CRP, TNF-α, and IL-6, in their serum compared to healthy individuals." (PMID 40771212, 2025). "The polyphenols extracted from purple potato leaves inhibited the levels of IL-1β, IL-6, and TNF-α, as well as serum creatinine, and also decreased the levels of expression of XOD in the liver of hyperuricemia mice, thus protecting the kidney." (PMID 38674582, 2024). "A similar study observed that L. plantarum Q7downregulated the levels of IL-1β, TNF-α, and MDA in hepatic and nephritic homogenate, indicating improved antioxidant activity and relief inflammation symptoms in the treatment of hyperuricemia mice." (PMID 38674582, 2024). "The geniposide-phospholipid complex reduces levels of inflammatory cytokines (TNF-α, IL-6, and IL-1β) in hyperuricemic mice and regulates the PI3K/AKT/NF-κB signaling cascade to improve post-hyperuricemia chronic kidney disease." (PMID 38094893, 2023).
hyperuricemia (continued). "In this study, the expression of TNF-α was increased as early as 1h and reached the peak at 24h in tubular cells, which might create a vicious circuit leading to a sustained chemokines production and inflammatory infiltration in the circumstance of hyperuricemia." (PMID 22761883, 2012). "Hyperuricemia triggers several inflammatory signaling pathways, with the TLR4/NF-κB axis being especially important in promoting the release of pro-inflammatory cytokines such as IL-1β, MCP-1, and TNF-α." (PMID 40963680, 2025). "One animal study on mice with hyperuricemia found that CGA could protect against elevated levels of UA, BUN, Cr, and reduce inflammation through the inhibition of LPS, IL-1β, and TNF-α among other inflammatory factors and related signaling pathways." (PMID 40821993, 2025). "There have studies indicated that the levels of inflammatory markers, including interleukin-6 (IL-6), tumour necrosis factor-α (TNF-α) and transforming growth factor-β1 (TGF-β1), are markedly elevated in individuals with hyperuricaemia in comparison to those in a healthy state." (PMID 39258191, 2024). "Patients with hyperuricemia had significantly higher values of FGF23 and TNF-α compared with those without hyperuricemia." (PMID 39768960, 2024). "Patients with hyperuricemia had lower eGFR and significantly higher levels of FGF23 and TNF-α than those without hyperuricemia." (PMID 39768960, 2024). "Hyperuricemia is accompanied by inflammatory markers, including IL-6, IL-18, hs-CRP, and TNF-α." (PMID 35453642, 2022). "In controls, associations with hypoalphalipoproteinemia, non-HDL-C, apolipoprotein B, hyperuricemia, TNF-α, IL-6, IL-15, valvular calcification, and subclinical hypothyroidism were observed." (PMID 33802675, 2021). "The core targets of Plantaginis Herba for the treatment of hyperuricemia were AKT1, mitogen-activated protein kinase 3 (MAPK3), MAPK1, tumor necrosis factor (TNF), prostaglandin-endoperoxide synthase 2 (PTGS2), sirtuin 1 (SIRT1), estrogen receptor 1 (ESR1), and androgen receptor (AR)." (PMID 33897800, 2021). "On the other hand, in controls, the polymorphisms were associated with hypoalphalipoproteinemia, non-HDL cholesterol, apolipoprotein B, hyperuricemia, TNF-α, IL-6, IL-15, valvular calcification, and subclinical hypothyroidism." (PMID 33802675, 2021). "Interleukin-6 (IL-6), tumor necrosis factor-alpha (TNF-α), and high sensitive C-reactive protein (hs-CRP) were also measured in order to determine the relationship of indices of inflammation with VAI and hyperuricemia." (PMID 29734946, 2018). "The diverse expression patterns might suggest different regulation mechanisms of TNF-α and RANTES in hyperuricemia." (PMID 22761883, 2012). "The findings showed that it was primarily involved in MAPK signaling pathway, IL-17 signaling pathway, TNF signaling pathway, VEGF signaling pathway, Toll-like receptor signaling pathway and PI3K-Akt signaling pathway, which may be the main targets for hyperuricemia treatment." (PMID 41009565, 2025). "Notably, Shiwei-Ruxiang powder has been observed to ameliorate renal impairment by diminishing CRE and BUN levels, while also counteracting the concentrations of pro-inflammatory agents like TNF-α and IL-1β, along with the expression of phospho-p38 MAPK, within hyperuricemia mice." (PMID 38094893, 2023). "It is noteworthy that hyperuricemia may stimulate inflammatory leukocytes through epigenetic modification such as histone methylation, even without MSU crystals, thereby increasing production of IL-1β, IL-6, and TNF-α." (PMID 33568990, 2020).
mood disorder (71 papers, 2013 to 2025). A cognitive disorder a disturbance in which the person's mood is hypothesized to be the main underlying feature. "Its expression is modulated by pro-inflammatory cytokines such as TNF-α and IL-1β, which are also implicated in mood disorders." (PMID 40491453, 2025). "LPS administration is known to elevate cytokine levels such as IL-1β, IL-6, and TNF-α, which contribute to neuroinflammation and are implicated in mood disorders." (PMID 40487411, 2025). "Several inflammatory components have been associated with the pathophysiology and treatment of mood disorders, including interleukin (IL)-6, prostaglandin (PG) E2, tumor necrosis factor (TNF)-α, and nuclear factor (NF)-κB." (PMID 39458912, 2024). "Studies indicate that carotenoids can inhibit nuclear factor-kappa B (NF-κB) and downregulate pro-inflammatory cytokines such as interleukin-6 and tumor necrosis factor-α, reducing neuroinflammation associated with mood disorders." (PMID 39749353, 2024). "We found a significant overlap for 6 hub genes (ADM, CITED2, IER5, NFKBIZ, SERTAD1, TNF) with similar co-expression and dysregulation patterns associated with mood disorder." (PMID 35386281, 2022). "It has been proposed that IL-1β, IL-6, and TNFα can directly modulate neuronal plasticity and cause mood disorders." (PMID 33402212, 2021). "The most prominent cytokines associated with mood disorders include: interleukin-1 beta (IL-1ß), interleukin-6 (IL-6), tumor necrosis factor alpha (TNF-alpha), and C-reactive protein (CRP)." (PMID 34113269, 2021). "TNF and IL-1β, like other pro-inflammatory cytokines, have been convincingly associated with mood disorders both in humans and rodents, and their levels increased in serum and CSF of MS patients, and in EAE brains." (PMID 27589957, 2016). "TNFα increase associates with malaise and mood disorders in patients with chronic fatigue syndrome, clearly underlying the important pathogenic role of this proinflammatory cytokine." (PMID 23710202, 2013). "TNF-α is recognized as a neuromodulator in the brain and has been implicated in the pathophysiology of mood disorders, with evidence suggesting that its signaling pathways may serve as potential targets for antidepressant drug development." (PMID 40004109, 2025). "It has been proposed that distribution in the peripheral immune system and subsequent over-activation of pro-inflammatory cytokines, including interleukin 1 (IL-1), IL-6, and tumor necrosis factor-alpha (TNF-α), have long been associated with the development of mood disorders." (PMID 41255494, 2025). "Neuroinflammation has been increasingly implicated in mood disorders, with elevated pro-inflammatory cytokines such as interleukin-6 (IL-6), tumor necrosis factor-alpha (TNF-α), and C-reactive protein (CRP) contributing to neuronal dysfunction and treatment resistance." (PMID 40969698, 2025). "Another key cytokine implicated in mood disorders is tumor necrosis factor-alpha (TNF-α)." (PMID 40004109, 2025). "Indeed, elevated peripheral inflammatory cytokine levels (IL−6, IL-1beta and TNF-alpha) have been associated with mood disorder development." (PMID 35625901, 2022). "Mood disorders are associated with chronic low-grade systemic inflammation accompanied by increased circulating pro-inflammatory cytokines and other pro-inflammatory mediators (interleukins, TNF-α), targeting all tissues including the brain." (PMID 36142325, 2022). "Furthermore, proinflammatory cytokine expression and circulating levels, like interferon gamma (INFγ), TNFα, IL-6, and IL-1β, are associated with mood disorder symptoms." (PMID 32377159, 2020). "In addition, studies have revealed that inflammation in the brain was associated with developing mood disorders, including BD, and that TNF-α was a critical cytokine in pathophysiology." (PMID 29929549, 2018). "In SLE, sera TNF-α levels are independently associated with mood disorders." (PMID 26732584, 2016).
mood disorder (continued). "Although IL-6 seems to be reliably activated by mental stress and to play an important role in mood disorders, other cytokines including TNF-α, IL-1ra and IL-1β appear to be relevant in the association of sedentary behaviour and mood but were not assessed in this study." (PMID 26294364, 2016). "Based on the large body of data suggesting that elevated TNF-α levels are associated with increased risk for mood disorders (among other psychiatric illnesses), we hypothesized that the potent anti-TNF-α effect of PTF would be associated with a prominent antidepressant-like effect." (PMID 36145284, 2022). "In addition, increased inflammation markers and pro-inflammatory cytokines, such as tumor necrosis factor-alpha and interleukin-6, in patients with mood disorders may offer another plausible explanation for the association of these mood disorders with NAFLD." (PMID 33537324, 2020). "Elevated levels of pro-inflammatory cytokines such as IL-6, TNF-α, and C-reactive protein (CRP) are commonly observed in individuals with inflammatory depression and have been linked to increased vulnerability to mood disorders." (PMID 41162174, 2025). "Stress-induced increases in LPS are paralleled by higher levels of proinflammatory cytokines, such as interleukin-6 (IL-6) and tumor necrosis factor-alpha (TNF-α), which have also been implicated in mood disorders." (PMID 38476949, 2024). "Mood disorders are accompanied by chronic systemic inflammation and increased plasma levels of pro‐inflammatory cytokines such as tumor necrosis factor‐alpha (TNF‐α) and interleukin‐6 (IL‐6)." (PMID 37933420, 2023). "TNF‐α antagonists had recently attracted interest as potential therapeutic compounds for mood disorders." (PMID 34590391, 2022). "Both the inflammatory cytokines interleukin-17 and tumor necrosis factor-alpha were increased in patients with perinatal mood disorders." (PMID 36032225, 2022). "Our study revealed significantly lower IL-8 and TNF-alpha levels in depressed patients compared to hypomanic/manic adolescents and young adults with mood disorders." (PMID 36032249, 2022). "In this regard, recently, concerns have been raised regarding the efficacy of selective TNF-α antagonists as a therapeutic strategy for mood disorders." (PMID 33921721, 2021). "Copious studies have consistently shown that patients with mood disorders have increased levels of plasma tumor necrosis factor (TNF)-α." (PMID 33921721, 2021). "Among the various anti-inflammatory drugs that have been explored as a potential treatment for mood disorders, selective TNF-α antagonists were given special attention." (PMID 33921721, 2021). "This process, also called “cytokine induced mood-disorder” can be induced by the systemic release of inflammatory cytokines including tumor necrosis factor alpha (TNFα), interleukin-6 (IL-6) and interleukin-1 beta (IL-1β)." (PMID 31734534, 2019). "In murine stress models, TNF has also been reported to upregulate indoleamine 2,3-dioxygenase (IDO) implicated as biological mediator of inflammation-related mood disorders." (PMID 30057531, 2018). "Studies conducted with mouse models show that mice given TNF-α injections exhibit mood disorders." (PMID 41317200, 2025). "Leptin is involved in neuroimmune interactions that link obesity, inflammation, and mood disorders, as it stimulates the release of proinflammatory cytokines such as IL-6, TNF-α, and IFN-γ, which are well-established activators of IDO1, thereby increasing the degradation of Trp through the KP." (PMID 41516008, 2025). "Infliximab, a tumor necrosis factor antagonist, has also been studied for mood disorders." (PMID 37762207, 2023). "Inflammatory markers and pro-inflammatory cytokines, including tumor necrosis factor-alpha and interleukin-6 may also potentiate mood disorders." (PMID 36275825, 2022). "Our study revealed alterations in TNF-alpha and IL-8 levels in youth with mood disorders." (PMID 36032249, 2022).
mood disorder (continued). "Findings from previous research showed that an imbalance between pro- and anti-inflammatory cytokines demonstrated through a higher ratio of TNF-α/IL-10 and IL-6/IL-10 in the brain of animals exposed to chronic mild stress, may contribute to mood disorders." (PMID 33810574, 2021). "Therefore, it is important to continue studying the therapeutic mechanism of action and effectiveness of selective TNF-α antagonists as a treatment for mood disorders." (PMID 33921721, 2021). "Therefore, new randomized, placebo-controlled clinical trials are necessary for direct examination of the mood-modulating effects of TNF-α antagonists in patients with mood disorders." (PMID 33921721, 2021). "A range of anti-inflammatory agents, including aspirin, minocycline, N-acetylcysteine, curcumin, anti-TNF-α agents, celecoxib, and omega-3 fatty acids are being investigated as an adjunct to treatment as usual for use in mood disorders, and the extant, albeit preliminary, evidence shows promise." (PMID 25889215, 2015). "This dysregulation may directly or indirectly influence sick behaviours, as the enhanced release of TNF-α within the brain contributes to the development of mood disorders and mental sickness." (PMID 23710202, 2013). "Indeed, preclinical and clinical studies have repeatedly demonstrated that an increase in the expression and activation of this inflammasome induces a higher release of cytokines, such as TNF-α, IL-1β, and IL-6, which have been shown to be elevated in individuals with this mood disorder." (PMID 36613574, 2022). "Elevated TNF-α levels in the PFC of GDM rats align with accumulating evidence implicating neuroinflammation in the pathophysiology of metabolic and mood disorders." (PMID 41399726, 2025). "Finally, the significant allelic ratio variation of SLA-DRB1 in the amygdala, combined with its known importance in regulating pro-inflammatory cytokines (e.g., IL-1β, IL-6, TNF-α) and microglial activation, supports its involvement in immune regulation and stress-related mood disorders." (PMID 40969342, 2025). "Specific inflammatory markers such as TNF-α, IL-1β, CRP, and TSPO may be commonly involved in the pathogenesis of both SUD and mood disorders." (PMID 35558424, 2022). "Higher levels of pro-inflammatory cytokines (e.g., tumor necrosis factor TNFα, interleukin IL6 and IL1β) in the central nervous system (CNS) have been suggested to contribute to the pathophysiology of neuropathic pain and the related mood disorder comorbidities." (PMID 36675275, 2023). "Studies have also shown that inflammatory markers may discriminate between treatment-resistant and non-resistant mood disorder patients, with the augmented levels TNF-α, IL-1β, and BDNF as markers of poorer antidepressant response." (PMID 35558424, 2022). "Thus, this systematic review aimed to summarize current evidence supporting the role of TNF‐α antagonists in inducing secondary manic episodes or exacerbating a mood switch in patients with or without mood disorders." (PMID 34590391, 2022).